VSX1 (visual system homeobox 1)
Description:
Binds to the 37-bp core of the locus control region (LCR) of the red/green visual pigment gene cluster. May regulate the activity of the LCR and the cone opsin genes at earlier stages of development. Dispensable in early retinal development (By similarity).
Synonyms: RINX; PPD; PPCD1; CAASDS; KTCN; KTCN1; PPCD
Tractability: No criterion of Open Targets' tractability assessment is met for any kind of drug.
Gene: Protein-coding gene on chromosome 20 (25,070,885 to 25,082,141, reverse strand). Ensembl gene ENSG00000100987.
Subcellular location: Nucleus
Subcellular location (Human Protein Atlas): Nucleoli
Gene Ontology:
Molecular function: protein binding; sequence-specific double-stranded DNA binding; DNA-binding transcription factor activity; DNA-binding transcription factor activity, RNA polymerase II-specific; transcription cis-regulatory region binding; DNA binding
Biological process: neuron development; regulation of DNA-templated transcription; visual perception; regulation of transcription by RNA polymerase II
Cellular component: chromatin; nucleus
Genetic constraint (gnomAD): Loss-of-function variants: 24 observed, 19.85 expected, observed/expected ratio (o/e) 1.21, 90% interval 0.87 to 1.69. The synonymous counts are far from expectation, so gnomAD's model fits this gene poorly and the ratio says little. Missense variants: 517 observed, 440.09 expected, observed/expected ratio (o/e) 1.17, 90% interval 1.09 to 1.26. Synonymous variants: 247 observed, 189.56 expected, observed/expected ratio (o/e) 1.3, 90% interval 1.17 to 1.45.
Homologues: Orthologues: chimpanzee VSX1 (99% identical), macaque VSX1 (96% identical), dog VSX1 (82% identical), pig VSX1 (80% identical), mouse Vsx1 (75% identical), rat Vsx1 (74% identical), guinea pig VSX1 (56% identical), tropical clawed frog vsx1 (51% identical), zebrafish vsx1 (48% identical), Caenorhabditis elegans dsc-1 (22% identical).
Diseases named in the same sentence as VSX1 in open-access papers:
VSX1 is named in the same sentence as 29 diseases in open-access papers, as found by Europe PMC text mining. Sharing a sentence is not in itself a finding about the gene and the disease. The quoted sentences say what the papers report.
keratoconus (32 papers, 2008 to 2026). A degenerative, structural disorder of the eye, characterized by a cone-shaped protrusion of the cornea. "Several mouse models have been developed to study corneal diseases, such as those with mutations in the transcription factor 4 (TCF4) gene for Fuchs' endothelial corneal dystrophy and mutations in the visual system homeobox 1 (VSX1) gene for keratoconus." (PMID 37642632, 2023). "Recent studies reported that VSX1 mutations played a pathogenic role in posterior polymorphous corneal dystrophy, and that the variant p.(His244Arg) in the VSX1 gene was observed in a sporadic female patient with bilateral keratoconus." (PMID 36463181, 2022). "Mutations in the VSX1 gene for distinct inherited corneal dystrophies, posterior polymorphous dystrophy and keratoconus, have been identified." (PMID 32111086, 2020). "Despite this poor coverage, a number of previously reported VSX1 variants in keratoconus were sufficiently covered for analysis." (PMID 29924831, 2018). "VSX1, which encodes a vertebrate paired-like homeodomain transcription factor with known ocular expression, is the most studied gene in keratoconus." (PMID 29924831, 2018). "The other missense sequence variant c.7672G > T was found in the second exon of the VSX1 gene in two cases of sporadic keratoconus." (PMID 28950846, 2017). "p.Arg131Pro (replacing the amino acid arginine with proline) has not been reported previously, so this work adds to the range of variants in the VSX1 gene and suggests the role of this novel variant in keratoconus." (PMID 28950846, 2017). "The results revealed four nucleotide sequence variants of the VSX1 gene in Chinese sporadic keratoconus patients, including two missense sequence variants and one SNP change (heterozygous and homozygous)." (PMID 28950846, 2017). "One novel missense heterozygous sequence variant (p.Arg131Pro) was found in the first exon of the VSX1 gene in one keratoconus patient." (PMID 28950846, 2017). "To investigate the possibility of VSX1 being a candidate susceptibility gene for Chinese patients with sporadic keratoconus, we performed sequence screening of this gene in such patients." (PMID 28950846, 2017). "These earlier studies indicated the need for further study on the relationship between VSX1 pathogenic variations and sporadic keratoconus in different subsets of the keratoconus-affected population." (PMID 28950846, 2017). "One of the candidate genes strongly implicated in keratoconus is visual system homeobox gene 1 (VSX1) localized to chromosome 20 p11–q11." (PMID 28950846, 2017). "Since the first report by Heon and colleagues numerous studies have evaluated the association of variants in VSX1 and keratoconus." (PMID 28932336, 2017). "The sequence variant c.5427G > C was found in the first exon of the VSX1 gene in one case of sporadic keratoconus." (PMID 28950846, 2017). "A number of other studies, further showed the presence of VSX1 variants in keratoconus patients from different ethnic populations." (PMID 23506487, 2013). "Mutations in the visual system homeobox 1 (VSX1) gene have been described at a low frequency in keratoconus and posterior polymorphous corneal dystrophy (PPCD)." (PMID 23592923, 2013). "Other recent studies also demonstrate segregation of other VSX1 probable pathogenic changes with keratoconus." (PMID 23592923, 2013). "Several factors contribute to this debate, but one point is the small number of cases of PPCD and keratoconus in which changes in VSX1 are described, despite probable pathogenic changes being described since 2002 in multiple population cohorts." (PMID 23592923, 2013). "The R166W VSX1 mutation was also initially found in an isolated case of keratoconus with visual impairment for whom a corneal graft was required in adulthood." (PMID 22171159, 2011). "Our initial molecular genetic studies conducted to identify the role of VSX1 in the causation of keratoconus had identified a novel mutation in one patient." (PMID 21365019, 2011).
keratoconus (continued). "Six of the VSX1 potential mutations, p.L17P, p.N151S, p.G160V, p.R166W, p.Q175H, and p.G239R were identified exclusively in keratoconus patients and in their relatives showing corneal abnormalities, but these mutations were absent in the controls." (PMID 21976959, 2011). "Mutations in the visual system homeobox 1 (VSX1) gene in keratoconus have been reported in different studies." (PMID 21139977, 2010). "In a recent study (2009) from India, VSX1 was screened in 66 keratoconus cases and a potentially pathogenic change (p.Q175H) was identified in one case only." (PMID 21139977, 2010). "In the light of previous studies, there is still insufficient evidence for the pathogenic role of VSX1 alone in causation of keratoconus." (PMID 19956409, 2009). "The present study was undertaken in order to search for genetic variations of the VSX1 gene in the Indian population and to explore its role in causation of keratoconus." (PMID 19956409, 2009). "To conclude, to the best of our knowledge this is the first report from the Indian subcontinent exploring the causative role of the VSX1 gene in keratoconus." (PMID 19956409, 2009). "Mutational analysis of VSX1 was carried out in 66 unrelated Indian patients affected with keratoconus in comparison to 100 controls." (PMID 19956409, 2009). "Q175H is a novel mutation, identified in the present study, adding to the database of mutations in the VSX1 gene and supporting its role in keratoconus." (PMID 19956409, 2009). "One of the strongly implicated candidate genes for keratoconus is Visual System Homeobox 1 (VSX1) localized to 20p11-q11." (PMID 19956409, 2009). "This is the first report from the Indian subcontinent exploring the role of VSX1 in the causation of keratoconus." (PMID 19956409, 2009). "For example, VSX1 can function as a transcriptional repressor in the terminal differentiation of a subset of bipolar cells, and a VSX1 mutation that impairs DNA binding and causes keratoconus in humans hindered repressor function." (PMID 36463181, 2022). "Our work suggests that VSX1 sequence variants might be involved in the pathogenesis of sporadic keratoconus, but their precise role in disease causation requires further investigation." (PMID 28950846, 2017). "Therefore, it was believed that p.Gly160Val of the VSX1 gene increases the risk of the onset of keratoconus." (PMID 28950846, 2017). "Several studies have identified mutations in VSX1 as a cause of keratoconus development in multiple ethnic populations, and VSX1 could be a strong candidate gene for keratoconus." (PMID 23592922, 2013). "This led to the assumption that mutations in the VSX1 gene may be involved in pathogenesis of keratoconus." (PMID 23506487, 2013). "Regarding the role of VSX1 in keratoconus, one of the most recent publications on this subject looked at an Italian cohort of 302 patients with keratoconus (the largest series published to date) and found probable pathogenic changes in VSX1 in 3.2% of the affected population." (PMID 23592923, 2013). "A large debate exists in the research community whether the VSX1 variations identified in keratoconus have to be regarded as disease-related mutations or simply nonpathogenic variants." (PMID 21976959, 2011). "The role of VSX1/Vsx1 in the corneal dystrophies keratoconus and posterior polymorphism dystrophy (PPCD1) and, the issue of whether it is expressed in the cornea has been a subject of considerable controversy." (PMID 21437200, 2011). "We reported a mutation Q175H in VSX1 in an individual diagnosed with keratoconus." (PMID 21365019, 2011). "Mutations in VSX1 gene have been identified in association with keratoconus." (PMID 21139977, 2010). "VSX1 mutations are responsible for a very small fraction of all observed keratoconus cases." (PMID 21139977, 2010).
keratoconus (continued). "Combined analysis of MAF value, pathogenicity analysis, and family co-segregation ruled out the possibility of other keratoconus genes or novel variants, as whole exome sequencing was performed on these KC patients with VSX1 sequence variation sites." (PMID 36999054, 2023). "VSX1 gene variants may play an important role in the development of keratoconus." (PMID 36585686, 2022). "To date, few disease-causing mutations of VSX1 have been linked to familial and sporadic keratoconus (KC) in humans." (PMID 25963163, 2015). "However, it is unclear whether and how mutations in VSX1 contribute to the pathogenesis of keratoconus." (PMID 25254113, 2014). "Mutations in VSX1 were reported associated with craniofacial abnormalities, empty sella tunica, and abnormal retinal cells, but more frequently and controversially with several corneal dystrophies and ectasias, specifically keratoconus and posterior polymorphous corneal dystrophy (PPCD)." (PMID 23592923, 2013). "Therefore, the VSX1 gene might have a small effect by itself, yet operate in conjunction with other genes or environmental factors in causation of keratoconus." (PMID 19956409, 2009). "VSX1 (Visual System Homeobox 1) was one of the first candidate genes proposed for keratoconus, based on rare familial cases." (PMID 41595486, 2026). "The 50 sporadic keratoconus patients and 50 control subjects recruited for this study underwent screening of the entire coding region and exon–intron junctions of the VSX1 gene by direct sequencing of DNA." (PMID 28950846, 2017). "This suggested that there were no sequence variants with a large insertion or deletion in the five exons of the VSX1 gene in the sporadic keratoconus patients." (PMID 28950846, 2017). "In this study, we added one novel missense sequence variation (p.Arg131Pro) in the coding region of the VSX1 gene to the range of VSX1 coding region variations observed in patients with sporadic keratoconus from China." (PMID 28950846, 2017). "Despite elucidate the etiology and the disease progression were conducted by numerous research, VSX1 is the only gene indicated as a vital genetic factor in determining the keratoconus." (PMID 28950846, 2017). "In summary, the p.Arg131Pro, p.Gly160Val, and c.8326G > A variations in the VSX1 gene were identified for the first time in Chinese patients with sporadic keratoconus." (PMID 28950846, 2017). "The VSX1 gene coding regions, including exon-intron boundaries were screened by direct sequencing analysis in 117 sporadic cases of keratoconus." (PMID 23506487, 2013). "This study reports the presence of pathogenic mutations in VSX1 in PPCD and keratoconus, including a novel disease-causing variant." (PMID 23592923, 2013). "In this study, we have undertaken the sequence analysis of coding regions of VSX1 gene in order to determine its genetic involvement in South Indian patients with sporadic form of keratoconus." (PMID 23506487, 2013). "The aim of the present study is to investigate the role of VSX1 gene in patients with sporadic cases of keratoconus from South India." (PMID 23506487, 2013). "The role of VSX1 in the pathogenesis of keratoconus and posterior polymorphous dystrophy has been debated in the literature since the gene was first described in 2002." (PMID 23592923, 2013). "The phenotypic heterogeneity of VSX1 with involvement in keratoconus and PPCD is feasible as the disorders share a potential common mode of involvement of the posterior surface of the cornea, specifically Descemet’s membrane." (PMID 23592923, 2013). "Mutational screening of 66 unrelated patients with keratoconus (27 familial cases; 39 sporadic cases) from the European population, showed a minor role of VSX1 in the pathogenesis of keratoconus." (PMID 23506487, 2013).
keratoconus (continued). "Two of these genes have been related to ophthalmologic disorders, including age related macular degeneration (HMCN1) and keratoconus (VSX1) and several have been related to neurologic disorders (IKBKAP, SGCG, SACS, ARHGEF10, and CACNA1S)." (PMID 23139751, 2012). "In spite of a huge amount of research conducted to elucidate the etiology and the disease progression, VSX1 is the sole gene indicated as an important genetic factor in determining the keratoconus." (PMID 21976959, 2011). "Eight dominant VSX1 missense mutations associated with Posterior Polymorphous Corneal Dystrophy 1 (PPCD1; OMIM 122000) and keratoconus (OMIM 148300) have been identified." (PMID 21437200, 2011). "Totally, VSX1 sequence variations were found in 42 out of 1,350 (3.1%) keratoconus probands and in seven out of 1,412 (0.49%) controls." (PMID 21976959, 2011). "In this study, we report the mutational analysis results for VSX1, LOX, SPARC, TIMP3, and SOD1, performed in a large cohort of Italian subjects affected by sporadic and familial keratoconus." (PMID 21976959, 2011). "The enntire coding region of VSX1, including intron-exon boundaries were amplified in keratoconus cases (n=50) and controls (n=50)." (PMID 21139977, 2010). "Initially VSX1 was chosen for screening mutations in posterior polymorphous corneal dystrophy (PPCD) and keratoconus." (PMID 21139977, 2010). "In this study we present the results of VSX1 gene analysis in 50 keratoconus patients and controls from north India." (PMID 21139977, 2010). "Mutations in the VSX1 transcription factor have been reported in patients affected with PPCD, keratoconus, or a combination of both phenotypes." (PMID 18253095, 2008). "Different groups have reported mutations involving functional domains of VSX1 in patients affected with PPCD, keratoconus, or a combination of both phenotypes." (PMID 18253095, 2008). "Variants of VSX1 and TGFBI genes identified in both the clinically diagnosed and subclinical patients may cause the keratoconus through an autosomal dominant inheritance pattern, with different variable expressivity." (PMID 34136477, 2021). "Nonetheless, the VSX1 gene has not been definitively demonstrated to play a causal role in keratoconus." (PMID 32111086, 2020). "All exons of the VSX1 gene in sporadic keratoconus patients were amplified by PCR." (PMID 28950846, 2017). "In the third intron of the VSX1 gene, the substitution of G > A at nucleotide position 8326 (c.8326G > A) was identified, which was present in heterozygous form in three cases of sporadic keratoconus and in four controls." (PMID 28950846, 2017). "Overall, our results demonstrate the existence of SNPs in the VSX1 gene in the Chinese population, and suggest that sporadic keratoconus patients from different ethnic groups may have the same pathogenesis." (PMID 28950846, 2017). "In the present study, PCR-SSCP and direct DNA sequencing techniques were used to examine nucleotide variations in the five exons and splicing regions of introns of the VSX1 gene in 50 unrelated Chinese patients with keratoconus, which were compared with the sequences in 50 controls." (PMID 28950846, 2017). "Furthermore, disease alleles were observed for other autosomal dominantly inherited degenerative diseases of sensory function, including retinitis pigmentosa (SEMA4A, RP1), deafness (MYO1A), glaucoma (CYP1B1, OPTN, WDR36), and keratoconus (VSX1)." (PMID 25333069, 2014). "A large number of variations including two novel frameshift mutations in mitochondrial complex I (ND1-6) gene of the mitochondrial genome have been reported in keratoconus patients negative for VSX1 mutations." (PMID 25254113, 2014). "Although VSX1 only accounts for rare cases, it still remains the most studied keratoconus gene." (PMID 25254113, 2014). "This study aims to determine whether VSX1 contributes to the genetic pathogenesis of keratoconus and PPCD in a New Zealand population, and includes analysis of a Polynesian population." (PMID 23592923, 2013).